KAT8 (lysine acetyltransferase 8)
Description:
Histone acetyltransferase that catalyzes histone H4 acetylation at 'Lys-5'- and 'Lys-8' (H4K5ac and H4K8ac) or 'Lys-16' (H4K16ac), depending on the context. Catalytic component of the MSL histone acetyltransferase complex, a multiprotein complex that mediates the majority of histone H4 acetylation at 'Lys-16' (H4K16ac), an epigenetic mark that prevents chromatin compaction. H4K16ac constitutes the only acetylation mark intergenerationally transmitted and regulates key biological processes, such as oogenesis, embryonic stem cell pluripotency, hematopoiesis or glucose metabolism (By similarity). The MSL complex is required for chromosome stability and genome integrity by maintaining homeostatic levels of H4K16ac. The MSL complex is also involved in gene dosage by promoting up-regulation of genes expressed by the X chromosome (By similarity). X up-regulation is required to compensate for autosomal biallelic expression (By similarity). The MSL complex also participates in gene dosage compensation by promoting expression of Tsix non-coding RNA (By similarity). As part of the NSL histone acetyltransferase complex, catalyzes histone H4 acetylation at 'Lys-5'- and 'Lys-8' (H4K5ac and H4K8ac) at transcription start sites and promotes transcription initiation. The NSL complex also acts as a regulator of gene expression in mitochondria: KAT8 associates with mitochondrial DNA and controls expression of respiratory genes in an acetyltransferase-dependent mechanism. Acts as an inhibitor of antiviral immunity by acetylating IRF3, preventing IRF3 recruitment to promoters (By similarity). Acts as a regulator of asymmetric division in muscle stem cells by mediating acetylation of PAX7 (By similarity). Acts as a regulator of epithelial-to-mesenchymal transition as part of the NSL complex by mediating acetylation of KDM1A/LSD1. The NSL complex is required for nuclear architecture maintenance by mediating acetylation of LMNA (By similarity). Promotes mitochondrial integrity by catalyzing acetylation of COX17 (By similarity). In addition to protein acetyltransferase activity, able to mediate protein propionylation.
Synonyms: hMOF; MOF; MYST1; FLJ14040; LIGOWS; ZC2HC8
Tractability: Small molecule: a structure with a bound ligand is known; a high-quality ligand is known; it has a high-quality binding pocket. PROTAC: ubiquitination databases record sites on it; its protein half-life has been measured; a small molecule that binds it is known.
Target class: Epigenetic regulator; Writer; Histone acetyltransferase; MYST family
Gene: Protein-coding gene on chromosome 16 (31,114,489 to 31,131,393, forward strand). Ensembl gene ENSG00000103510.
Subcellular location: Nucleus; Chromosome; Mitochondrion
Subcellular location (Human Protein Atlas): Nucleoplasm
Pathways (Reactome):
Chromatin organization: HATs acetylate histones
Gene expression (Transcription): Formation of WDR5-containing histone-modifying complexes
Gene Ontology:
Molecular function: histone acetyltransferase activity; histone H4 acetyltransferase activity; histone H4K16 acetyltransferase activity; histone H4K5 acetyltransferase activity; histone H4K8 acetyltransferase activity; protein binding; protein propionyltransferase activity; protein-lysine-acetyltransferase activity; RNA polymerase II-specific DNA-binding transcription factor binding; transcription coactivator activity; acetyltransferase activity; DNA-binding transcription factor binding; enzyme binding; promoter-specific chromatin binding
Biological process: myeloid cell differentiation; negative regulation of DNA-templated transcription; negative regulation of epithelial to mesenchymal transition; neurogenesis; positive regulation of DNA-templated transcription; positive regulation of transcription initiation by RNA polymerase II; regulation of autophagy; regulation of mitochondrial transcription; regulation of mRNA processing; transcription initiation-coupled chromatin remodeling; negative regulation of type I interferon production; oogenesis; positive regulation of skeletal muscle satellite cell differentiation; post-embryonic hemopoiesis; dosage compensation by inactivation of X chromosome; epigenetic regulation of gene expression; hemopoiesis; negative regulation of multicellular organismal process; regulation of cell differentiation; regulation of DNA-templated transcription
Cellular component: chromosome; histone acetyltransferase complex; mitochondrion; MLL1 complex; MSL complex; NSL complex; nucleoplasm; nucleus; NuA4 histone acetyltransferase complex; kinetochore; nuclear lumen; nuclear matrix
Genetic constraint (gnomAD): Loss-of-function variants: 40 observed, 61.12 expected, observed/expected ratio (o/e) 0.65, 90% interval 0.51 to 0.85. The upper end of that interval is the gene's LOEUF score, 0.85, which puts it in group 3 of 6, group 1 being the genes least tolerant of losing a copy. Missense variants: 387 observed, 581.36 expected, observed/expected ratio (o/e) 0.67, 90% interval 0.61 to 0.72. Synonymous variants: 278 observed, 244.38 expected, observed/expected ratio (o/e) 1.14, 90% interval 1.03 to 1.26.
Homologues: Orthologues: dog KAT8 (99% identical), guinea pig KAT8 (99% identical), rabbit KAT8 (99% identical), mouse Kat8 (98% identical), chimpanzee KAT8 (95% identical), macaque KAT8 (95% identical), pig KAT8 (95% identical), rat Kat8 (91% identical), tropical clawed frog kat8 (85% identical), zebrafish kat8 (83% identical), Drosophila melanogaster mof (52% identical), Caenorhabditis elegans mys-2 (40% identical), and 1 more. Paralogues in human: KAT6A (42% identical), KAT6B (41% identical), KAT5 (39% identical), KAT7 (38% identical), RSF1 (16% identical), PHF10 (13% identical), DPF1 (12% identical), DPF2 (11% identical), DPF3 (11% identical).
Diseases named in the same sentence as KAT8 in open-access papers:
KAT8 is named in the same sentence as 81 diseases in open-access papers, as found by Europe PMC text mining. Sharing a sentence is not in itself a finding about the gene and the disease. The quoted sentences say what the papers report.
breast carcinoma (14 papers, 2013 to 2025). "Specifically, KAT8 expression was reduced by over 75% in 41% of patients with primary breast cancer and 79% of patients with medulloblastoma." (PMID 40508066, 2025). "In MCF-7 and MDA-MB231 breast cancer cells, small interfering RNA-mediated KAT8 knockdown reduced global H4K16ac levels, silenced the pro-apoptotic gene PYD and CARD domain containing (PYCARD/TMS1/ASC), and inhibited apoptosis." (PMID 40508066, 2025). "For example, KAT8 knockout induced hyperproliferation in MCF-7 breast cancer cells." (PMID 40508066, 2025). "More importantly, in samples from individuals with cancer (lung cancer, melanoma, breast cancer and gastric cancer), KAT8 and IRF1 condensates were also observed, and the fluorescence intensities of both proteins were positively correlated with PD-L1 expression." (PMID 36894639, 2023). "In MDA-MB-231 breast cancer cells, KAT8 acetylated WSTF at lysine 426, promoting its phosphorylation at serine 158 and thereby enhancing its kinase and transcriptional activity, driving breast cancer cell proliferation, migration, and invasion." (PMID 40508066, 2025).
colorectal cancer (11 papers, 2016 to 2025). A primary or metastatic malignant neoplasm that affects the colon or rectum. "In colorectal cancer, lysine acetyltransferase 8 (KAT8) induces lactylation at the K408 site of the eukaryotic translation elongation factor 1 alpha 2 (eEF1A2)." (PMID 40589733, 2025). "Our findings uncover a novel mechanism that KAT8 acetylation-controlled lipolysis affects invasive and migratory potential in colorectal cancer cells." (PMID 36849520, 2023). "However, little is known about the effects of KAT8 or KAT8 acetylation besides autoacetylation on lipolysis in colorectal cancer cells." (PMID 36849520, 2023). "KAT8 suppresses HSL expression to further affect the invasive and migratory potential in colorectal cancer cells." (PMID 36849520, 2023). "In colorectal cancer, the depletion of KAT8 did not reduce p300 protein expression levels, indicating that KAT8 regulation of Kla is independent of p300." (PMID 40565047, 2025). "Lactylation of eEF1A2K408 supported tumorigenesis via increased protein synthesis, whereas deletion of KAT8 inhibited the growth of colorectal cancer in nude mice injected with HCT116 cells with or without KAT8 depletion." (PMID 39516356, 2024). "Taken together, our data reveals that KAT8 acetylation plays a critical role in lipolysis to further affect invasive and migratory potential of CRC cells, and it may serve as a potential target for colorectal cancer therapy." (PMID 36849520, 2023).
gastric cancer (9 papers, 2016 to 2025). A primary or metastatic malignant neoplasm involving the stomach. "Downregulation of KAT8 and its associated H4K16ac has been observed in renal cell carcinoma, ovarian cancer, hepatocellular carcinoma (HCC), and gastric cancer." (PMID 40508066, 2025). "In MGC-803 gastric cancer cells, capsaicin upregulated KAT8 and enhanced global H4K16ac levels, leading to G1 phase arrest and inhibited proliferation." (PMID 40508066, 2025). "Conversely, elevated KAT8 expression in MGC-803 gastric cancer cells increased H4K16ac levels, leading to cell cycle arrest at the G1 phase." (PMID 40508066, 2025). "Similarly, KAT8 expression was downregulated in 90.5% (19/21) of patients with renal cell carcinoma, and its levels correlated positively with survival in patients with liver and gastric cancer." (PMID 40508066, 2025). "Salicylate inhibited KAT8 expression, reduced H4K16ac in the mucin 1 (MUC1) promoter, downregulated AKT phosphorylation, and suppressed EMT in gastric cancer cells." (PMID 40508066, 2025). "We found that ALKBH5 expression and the levels of K235 acetylation of ALKBH5 and its acetyltransferase KAT8 are increased and its deacetylase HADC7 level is downregulated in liver and gastric cancers." (PMID 37369679, 2023). "KTM2A was found to have interactions with MEN1, MLL1 complex, ATR, KAT8, SP11, and PAX7 none of which have been implicated in gastric cancer before." (PMID 37287033, 2023).
ovarian carcinoma (9 papers, 2013 to 2025). A malignant neoplasm originating from the surface ovarian epithelium. "HCP5 was confirmed as one of the KAT8 (alias hMOF) downregulated genes by qPCR and ChIP in the hMOF siRNA knockdown HeLa cells and 20 of 28 clinically diagnosed ovarian cancer tissues." (PMID 31137555, 2019).
lung carcinoma (8 papers, 2015 to 2026). "Additionally, lysine acetyltransferase 8 (KAT8) acetylates PKM2 at K433, which is associated with DDP resistance in lung cancer." (PMID 40264038, 2025). "Ectopic expression of Cas9 and single guide RNAs (sgRNAs) targeting KAT8 in multiple cell lines (osteosarcoma cell line 143B, malignant melanoma cell line A375 and lung cancer cell line A549) significantly decreased the total protein and mRNA levels of PD-L1 with or without IFNγ exposure." (PMID 36894639, 2023). "Collectively, these findings define a CDK1-KAT8 signaling axis that promotes NSCLC proliferation through epigenetic regulation and suggest that targeting CDK1-dependent KAT8 phosphorylation may represent a potential therapeutic strategy for lung cancer." (PMID 42193906, 2026).
glioblastoma (7 papers, 2019 to 2025). The most malignant astrocytic tumor (WHO grade IV). "Our analysis showed that KAT8 expression was significantly lower in grade IV gliomas (glioblastoma) compared to grades I–III." (PMID 40259204, 2025). "Conversely, KAT8 is aberrantly upregulated in certain malignancies, including glioblastoma, oral tongue squamous cell carcinoma, NSCLC, thymic lymphoma, endometrial cancer, and thyroid cancer." (PMID 40508066, 2025). "H4K16 acetyltransferase MYST1/KAT8 contributes to glioblastoma progression by activating EGFR signaling." (PMID 34680038, 2021). "Notably, KAT8 is significantly upregulated in various malignancies, including thyroid carcinoma, glioblastoma multiforme, oral tongue squamous cell carcinoma, NSCLC, and thymic lymphoma, where it modulates cell proliferation." (PMID 40508066, 2025). "The negative correlation between KAT8 expression and apoptosis in glioblastoma cells, as revealed by single‐cell sequencing, was further validated by our in vitro experiments showing increased apoptosis upon KAT8 knockdown in glioma cell lines." (PMID 40259204, 2025). "Single‐cell sequencing data revealed a negative correlation between KAT8 expression and apoptosis in glioblastoma cells." (PMID 40259204, 2025). "KANSL2 gene encodes the KAT8 regulatory NSL complex subunit 2 protein, which is a KANSL protein family member belonging to the complex of lysine acetyl-transferase KAT8/MOF-NSL, and recently shown to regulate glioblastoma’s cancer stem-like properties that contribute to tumorigenesis." (PMID 32001790, 2020).
medulloblastoma (6 papers, 2013 to 2025). A malignant, invasive embryonal neoplasm arising from the cerebellum. "In a study analyzing 5102 medulloblastoma tissues, both mRNA and protein levels of KAT8 were markedly reduced compared to normal tissues, accompanied by decreased H4K16ac levels." (PMID 40508066, 2025). "For example, the down-regulation of hMOF (KAT8), a histone H4K16 acetyltransferase, has been linked to poor prognosis in medulloblastoma." (PMID 41228218, 2025).
Obesity (6 papers, 2018 to 2025). Accumulation of substantial excess body fat. "Findings from GWAS have highlighted rs9925964 SNP in KAT8 gene as a risk locus for obesity, an association possibly explained by data associating KAT8 with adipose tissue development and function, central control of metabolism, and diet-induced obesity." (PMID 36986146, 2023). "Interestingly, the CTSB, ZNF646, and KAT8 genes have been associated with obesity." (PMID 40722297, 2025).
Alzheimer disease (5 papers, 2021 to 2024). A progressive, neurodegenerative disease characterized by loss of function and death of nerve cells in several areas of the brain leading to loss of cognitive function such as memory and language. "We also found distinct variants associated with lung function and cognitive function in KAT8 (forced vital capacity and Alzheimer’s disease) and PTCH1 (forced vital capacity and forced expiratory volume in 1 s to forced vital capacity ratio with fluid intelligence and reaction time)." (PMID 39544701, 2024). "Variation in VKORC1 has been linked in a gene-based test to dementia/Alzheimer’s disease in the parents of participants, with suggestive evidence for an association for rs9923231 (p = 1.8×10–7), which was included in the genome-wide significant KAT8 locus." (PMID 33682710, 2021). "KAT8 inhibition may provide neuroprotective effects for Alzheimer’s disease (AD) by increasing lysosome formation." (PMID 38777823, 2024). "Furthermore, a local genetic correlation between Alzheimer’s disease and cerebellar volume was found in a locus that includes the Alzheimer’s disease’s lead SNP in KAT8, which further illustrates this gene’s key role in neurodegenerative disorders." (PMID 39544701, 2024).
hepatocellular carcinoma (5 papers, 2022 to 2025). A malignant tumor that arises from hepatocytes. "KAT8 was shown to acetylate fatty acid synthase (FASN) to further destabilize FASN and decrease de novo lipogenesis and tumor cell growth of human hepatocellular carcinoma." (PMID 36849520, 2023). "KAT8 (lysine acetyltransferase 8) primarily acetylates H4K16, along with certain non-histone proteins, and enhances the ESR1 signaling pathway through its acetylase activity in hepatocellular carcinoma." (PMID 39684286, 2024).
prostate carcinoma (5 papers, 2017 to 2025). A carcinoma that arises from epithelial cells of the prostate gland. "Therefore, KAT8 may regulate autophagy in breast and prostate cancers via GABARAPL1." (PMID 40508066, 2025). "In vitro KAT assays confirmed that salicylate directly inhibited PCAF/Kat2b, Tip60/Kat5 and hMOF/Kat8, and this inhibition was likely involved in the reversal of EMT in the metastatic prostate cancer cell line PC-3." (PMID 28717171, 2017).
colon cancer (4 papers, 2017 to 2025). "Also, the key regulation effect of KAT8 in lipolysis was found in colon cancer RKO and sw480 cells." (PMID 36849520, 2023).